G3BP1 (G3BP stress granule assembly factor 1)
Diseases named in the same sentence as G3BP1 in open-access papers (continued):
Sharing a sentence is not in itself a finding about the gene and the disease.
head and neck cancer (3 papers, 2013 to 2022). A primary or metastatic malignant neoplasm affecting the head and neck. "Over-expression of G3BP1 has been detected in a number of human cancers including breast, lung, prostate, colon, thyroid, esophageal, and head and neck cancers, and over-expression has also been associated with lymph node metastasis and worse survival in esophageal squamous cell carcinoma." (PMID 23341773, 2013).
lymph node metastasis (3 papers, 2013 to 2024). "We further studied the relationship between clinicopathological parameters, including gender, age, histological type, clinical stage, pathological degree and LNM (lymph node metastasis) status and overexpression of G3BP1, YB1, and p‐AKT proteins by chi‐square test." (PMID 31560169, 2019). "In multivariate analysis of the features of patients with NPC, positive expression of G3BP1 is identified as an independent poorer prognostic factor for patients with NPC, along with lymph node metastasis and distant metastasis." (PMID 38164170, 2024).
oesophageal cancer (3 papers, 2011 to 2024). "Loss of G3BP1 suppresses the proliferation, migration, and invasion of oesophageal cancer cells via inactivation of the Wnt/β-catenin and PI3K/AKT signalling pathways." (PMID 33579337, 2021).
pancreatic cancer (3 papers, 2021 to 2026). "Furthermore, the analysis showed that certain RNAs such as HUWE1, hsa-miR-6780b-5p, has_circ_0058208 and lnc-G3BP1-3:8 were found to be in central positions of the network, suggesting their importance in promoting pancreatic cancer progression on many levels." (PMID 35528956, 2021).
renal carcinoma (3 papers, 2021 to 2025). A carcinoma arising from the epithelium of the renal parenchyma or the renal pelvis. "And we discover that targeting Circ_0000798 to regular miR-589-5p/G3BP1 axis can inhibit the growth and motility of renal cancer cells." (PMID 40546967, 2025). "Furthermore, the resistance of renal cancer cells to sunitinib is mediated by the MALAT1/miR-362-3p/G3BP1 signaling axis." (PMID 35706002, 2022). "These evidences of the role of G3BP1 in RCC may provide some ideas for the exploration of SGs in the occurrence and development of renal cancer." (PMID 40546967, 2025). "Additionally, YBX1 is capable of interacting with G3BP1 to promote SPP1 upregulation, resulting in renal cancer invasion and metastasis." (PMID 34758833, 2021).
astrocytoma (2 papers, 2020 to 2022). "Expression of these genes did not correlate with survival in GBM, however these genes did predict survival in low-grade astrocytoma with exception of G3BP1 which trended to significance." (PMID 33203845, 2020). "We next performed a compound screen to identify compounds that can inhibit CLM-and NU7441-induced formation of FUSP525L-positive SGs without changing the formation of G3BP1-positive SGs as the 1st screen using mCherry-G3BP1-and Venus-FUSP525L-expressing U251 MG (KO) astrocytoma cell lines." (PMID 36606141, 2022).
Ataxia (2 papers, 2020 to 2024). Ataxia refers to impaired coordination of voluntary muscle movement. "While these data strongly support that the loss of G3BP1 prevents senescence-induced cancer, previous observations have shown that G3BP1 knockout mice exhibit neurological defects, such as ataxia-related phenotypes, and premature aging." (PMID 33020468, 2020). "However, G3BP1 inhibition leads to neonatal death, premature aging phenotype as well as the development of pathologies such as ataxia." (PMID 38360999, 2024).
atherosclerosis (2 papers, 2021 to 2022). A disease characterized by the build-up of fatty material and calcium deposition in the arterial wall resulting in partial or complete occlusion of the arterial lumen. "G3BP1 is a known regulator of atherosclerosis, and targeting this relay may help reduce atherosclerosis." (PMID 34526993, 2021).
cardiac hypertrophy (2 papers, 2015 to 2021). "Immunocytochemistry in cultured neonatal myocytes treated with ad-siG3bp1 in the presence of ET-1 confirmed that G3bp1 was required for development of cardiac hypertrophy." (PMID 26675618, 2015). "G3bp1 posttranscriptionally regulates miRNA-1 processing in the heart, and G3bp1 mediated downregulation of mature miRNA-1 levels is required for the derepression of its targets and increase in gene expression during cardiac hypertrophy." (PMID 26675618, 2015). "Conversely, knockdown of G3bp1 in hypertrophying cardiomyocytes inhibited downregulation of miR-1 and upregulation of its targets along with restricted hypertrophy, suggesting that G3bp1 is necessary for development of cardiac hypertrophy." (PMID 26675618, 2015). "G3bp1 has relatively high expression in the heart, and according to our data is increased during pressure-induced cardiac hypertrophy in mice." (PMID 26675618, 2015). "G3bp1 is upregulated during cardiac hypertrophy and restricts miR-1 processing by binding to its consensus sequence in the pre-miR-1-2 stem-loop." (PMID 26675618, 2015). "The expression of G3BP1 increases during cardiac hypertrophy." (PMID 34526993, 2021). "In this study we show that G3bp1 mediates downregulation of miR-1, which is necessary for the derepression of its targets that includes Eif4e and is required for the increase in protein synthesis during cardiac hypertrophy." (PMID 26675618, 2015). "Thus, G3BP1 plays an important role in the development of cardiac hypertrophy." (PMID 34526993, 2021). "Thus, we presumed that these differences might be the reason for differential regulation of pre-miR-1-1 and pre-miR-1-2 stem-loop by G3bp1, resulting in controlled decrease in mature miR-1 levels with induction of cardiac hypertrophy." (PMID 26675618, 2015). "In agreement with our previous data showing that downregulation of miR-1 is not sufficient for induction of cardiac hypertrophy, overexpression of exogenous G3bp1 in cardiomyocytes did not result in increase cell size or increase in total protein synthesis." (PMID 26675618, 2015). "In this study we show that downregulation of miR-1 with induction of cardiac hypertrophy is due to posttranscriptional regulation of pre-miR-1 by an endoribonuclease G3BP1 and not due to change in transcription of the primary transcript." (PMID 26675618, 2015). "Similar to miR-1 knockdown, G3bp1 overexpression is not sufficient for development of cardiac hypertrophy." (PMID 26675618, 2015). "Interestingly, overexpression of G3bp1 was not sufficient for the development of cardiac hypertrophy." (PMID 26675618, 2015).
cystic fibrosis (2 papers, 2020 to 2021). Autosomal recessive disorder caused by pathogenic variants in the CFTR gene (cystic fibrosis transmembrane conductance regulator), which encodes a chloride and bicarbonate channel expressed in epithelial cells, and follow the diagnosis criteria. "Indeed, G3BP1 was recently described to promote proteasomal function and inhibit accumulation of ubiquitinated protein aggregates associated with Parkinson’s (α-synuclein) and Cystic Fibrosis (CFTR-ΔF508), which were induced by p62 and USP10." (PMID 32992901, 2020). "Therefore, G3BP1 can be used as a therapeutic target for ubiquitinated protein aggregation-related diseases, such as Parkinson’s disease (PD) and cystic fibrosis." (PMID 34526993, 2021).
dengue (2 papers, 2015 to 2024). "G3BP1 and G3BP2 regulate expression of ISGs known to have broad antiviral activity, and are required for an IFN response against dengue and yellow fever viruses." (PMID 26001115, 2015).
endometrial cancer (2 papers, 2023 to 2025). Primary or metastatic malignant neoplasm involving the endometrium (mucous membrane that lines the endometrial cavity). "Recent studies have identified G3BP1 as both highly expressed and frequently mutated in endometrial cancer, with its expression positively correlating with ERα protein levels." (PMID 40521202, 2025).
heart failure (2 papers, 2026). Inability of the heart to pump blood at an adequate rate to meet tissue metabolic requirements. "G3BP1-Suc level was diminished in Myosin binding protein C3 (Mybpc3) knockout and transverse aortic constriction (TAC) operated mice, which developed heart failure (HF)." (PMID 42107065, 2026).
hepatic cancer (2 papers, 2022). "H19 lncRNA with m5C change specifically binds to G3BP1 protein, further leading to the accumulation of oncoprotein and promoting the occurrence and progression of liver cancer." (PMID 35686101, 2022). "However, although TIA1 silencing in these cells may impair SG formation (absence of G3BP1 positive SG when TIA1 is silenced in some cells), it only slightly impairs sorafenib resistance of hepatic cancer cells." (PMID 35406476, 2022).
inflammatory bowel disease (2 papers, 2022 to 2025). A spectrum of small and large bowel inflammatory diseases of unknown etiology. "The sensitivity of the pipelines allows detection of subtle morphologic alterations that warrant further investigation, as does the usage of G3BP1 as an inflammatory bowel disease stress marker." (PMID 41354404, 2025).
ischemic stroke (2 papers, 2025). A stroke disorder caused by obstruction of blood flow to the brain, due to thrombotic (local blood clot formation) or embolic (due to a blood clot or other material traveling from another site) event. "Now it is shown that Ras GTPase‐activating protein SH3 domain‐binding protein 1 (G3BP1) has the potential to serve as a therapeutic target for ischemic stroke." (PMID 41013906, 2025). "Procyanidin B3 and its derivatives can be potentially used for developing anti‐ischemic stroke agents by targeting G3BP1." (PMID 41013906, 2025). "By using the human brain tissue sections obtained from ischemic stroke patients, we found a consistent co‐localization between FUS, CD63, and the SGs marker protein G3BP1." (PMID 38924471, 2025).
male infertility (2 papers, 2013 to 2020). The inability of the male to effect fertilization of an ovum after a specified period of unprotected intercourse. "EGFR, the signalling dysfunction of which was associated with human male infertility, might be coregulated by FXR1, FXR2, and HNRNPA1 (all of these three bind EGFR from CLIP experiments), G3BP2, G3BP1, FMR1, and SRSF7." (PMID 32316190, 2020).
metastatic tumors (2 papers, 2015 to 2024). "Consistent with the subcutaneous tumorigenesis model, we found that the number of lung metastatic tumors was significantly higher in the G3BP1 overexpression group than in the control group, and injection of stattic partially reduced the number of tumors." (PMID 38164170, 2024). "Both 4T1-luc/G3BP1(−)-1 and 4T1-luc/G3BP1(−)-2 cells and a mixture of 4T1-luc/G3BP1(−)-1/2 cells were implanted into the mammary fat pad of mice (BALB/c) to examine their ability to form metastatic tumors." (PMID 25962958, 2015).
Obesity (2 papers, 2022 to 2023). Accumulation of substantial excess body fat. "In six m6A-RMRs upregulated in the obesity group, two regulators IGF2BP3 (RNA methyltransferase) and G3BP1 (m6A repelled RNA binding protein) were shared by obesity IS and obesity IR." (PMID 35211628, 2022). "Stress granules (G3BP1) were significantly induced by the HFD in both sexes; conversely, inflammatory (IL-1β) responses were observed only in the male liver and cochlea, consistent with phenotype HFD-induced obesity." (PMID 36810096, 2023).
proteinopathies (2 papers, 2021 to 2022). "VCP and its adaptor FAF2 were recently found to mediate the extraction of G3BP1 from stress granules induced by heat stress, leading to their disassembly, which establishes an interesting connection between stress granule dynamics and the pathogenesis of proteinopathies." (PMID 35164882, 2022).
Stroke (2 papers, 2023 to 2025). Sudden impairment of blood flow to a part of the brain due to occlusion or rupture of an artery to the brain. "RIC significantly increased G3BP1, TIA1, and DDX3X levels in mRNA and protein expressions at Day 3 after stroke." (PMID 37580991, 2023).
type 2 diabetes (2 papers, 2022 to 2025). "Transcriptomic profiling of laser capture microdissected islets from metabolically phenotyped human living donors in our LIDOPACO cohort had revealed that G3BP1 is downregulated in individuals with type 2 diabetes compared to normoglycemic donors." (PMID 40355555, 2025). "Here, we found that G3BP1, a stress granule marker downregulated in islets of subjects with type 2 diabetes, binds to insulin mRNA in glucose concentration-dependent manner." (PMID 40355555, 2025). "Moreover, impaired glucose stimulated insulin secretion in G3BP1−/− cells is concordant with evidence of G3BP1 downregulation in islets of patients with type 2 diabetes, who suffer from reduced insulin release." (PMID 40355555, 2025). "Therefore, it will be important to investigate further how AldoB overexpression in islets of patients with type 2 diabetes affects beta cell AMPKα/mTOR activities, mitochondrial function, the dynamics of G3BP1+/INS mRNA condensates, and thus insulin production and secretion." (PMID 40355555, 2025). "Among the 15 m6A-RMRs upregulated in four different tissues in type 2 diabetes, one regulator HNRNPA2B1 (reader) was shared by liver, subcutaneous adipose, and visceral adipose, and one regulator G3BP1 was shared by liver and visceral adipose." (PMID 35211628, 2022).
uveal melanoma (2 papers, 2021). A melanoma derived from melanocytes of the uveal tract. "A recent study reported that circ_0119872 promotes the malignancy of uveal melanoma cells by regulating the miR-622/G3BP1 axis." (PMID 34644734, 2021).
allergic disease (1 paper, 2022). An immune response that occurs following re-exposure to an innocuous antigen, and that requires the presence of existing antibodies against that antigen. "The East Asian-specific putative causal variants in G3BP1 were associated with autoimmune and allergic disease susceptibility." (PMID 35753705, 2022). "Our study newly identified six loci associated with allergic diseases (MIIP, CXCR4, SCML4, CYP1B1, ICOS and LINC00824) and four pleiotropic loci associated with both autoimmune and allergic diseases (PRDM2, G3BP1, HBS1L and POU2AF1)." (PMID 35753705, 2022). "We identified four loci shared between the six autoimmune and allergic diseases (rs10803431 at PRDM2, OR=1.07, p=2.3×10−8, rs2053062 at G3BP1, OR=0.90, p=2.9×10−8, rs2210366 at HBS1L, OR=1.07, p=2.5×10−8 in Japanese and rs4529910 at POU2AF1, OR=0.96, p=1.9×10−10 across ancestries)." (PMID 35753705, 2022).
asthma (1 paper, 2023). "Specifically, we sought to examine causal mediation between PBMC key drivers associated with asthma (PRF1 and NKG7 in the NK cell module; CAPZA2, ATP6AP2, CTSS, and RAB3D from the interleukin module) and nasal key drivers associated with asthma (G3BP1 and INADL from the nasal TCA module)." (PMID 37730635, 2023).
carcinoid (1 paper, 2014). "Western blot analyses confirmed that the expression of the EGR1 and G3BP1 proteins were reduced after re-introduction of miR-129-5p to both carcinoid cell lines." (PMID 25546138, 2014). "We showed that by inhibiting G3BP1 we can inhibit growth of carcinoid cells demonstrating that indeed this pathway is important in neuroendocrine carcinogenesis." (PMID 25546138, 2014). "To characterize the biology of EGR1 and G3BP1 in NETs, we examined their importance for growth of carcinoid cell lines." (PMID 25546138, 2014). "We found that knock down of EGR1 and G3BP1 inhibited the growth of carcinoid cell lines compared to controls." (PMID 25546138, 2014).
cardiomyopathy (1 paper, 2026). A disease of the heart muscle or myocardium proper. "We demonstrate a critical role for G3BP1 Suc at K413 in cardiac function by modulating the PI3K-AKT-mTOR pathway, providing new insights into the non-canonical function of G3BP1 in cardiomyopathy and HF pathogenesis." (PMID 42107065, 2026).
cerebral infarct (1 paper, 2025). "Strikingly, this chemical intervention shows translational potential, as ICA reduces cerebral infarct volume in ischemia models via G3BP1-dependent SGs remodeling." (PMID 41263030, 2025).
Cerebral ischemia (1 paper, 2023). Restriction of arterial blood supply to the brain associated with insufficient oxygenation to support the metabolic requirements of the tissue. "The results showed that the mRNA by RT‐qPCR assays and protein expressions of G3BP1 by Western blot analysis were transiently increased at 0 h after cerebral ischemia/reperfusion (R‐0 h) and then was decreased in the R‐24 h groups (p < 0.05)." (PMID 37580991, 2023). "In line with this, our study found that expressions of G3BP1, TIA1, and DDX3X33, 52 and the major components of SGs were transiently increased at 0 h after cerebral ischemia/reperfusion, and then decreased gradually until 24 h postreperfusion." (PMID 37580991, 2023).
Charcot-Marie-Tooth disease (1 paper, 2025). An inherited degenerative disorder involving the peripheral nerves. "Pathologically, dysregulation of G3BP1 may disrupt SGs homeostasis, as exemplified in Charcot-Marie-Tooth disease (CMT) where mutant proteins abnormally interact with G3BP1, inducing compositional alterations and functional impairment of SGs." (PMID 40546967, 2025).
cholangiocarcinoma (1 paper, 2026). A carcinoma that arises from the intrahepatic biliary tree (intrahepatic cholangiocarcinoma) or from the junction, or adjacent to the junction, of the right and left hepatic ducts (hilar cholangiocarcinoma). "In cholangiocarcinoma, KIF14 binds to the G3BP1/YBX1 complex, leading to the activation of the NF-κB pathway." (PMID 41507134, 2026).
dilated cardiomyopathy (1 paper, 2026). Cardiomyopathy which is characterized by dilation and contractile dysfunction of the left and right ventricles. "Mice injected with AAV9-G3BP1 (WT) developed typical phenotypes of dilated cardiomyopathy (DCM) and HF when compared to mice injected with AAV9-Ctrl and -G3BP1 (K411R) mice, suggesting a possible loss of functional effect of de-Suc at K411." (PMID 42107065, 2026).
disc degeneration (1 paper, 2023). "The roles of G3BP1 and mTOR signalling were further investigated in the in vivo disc degeneration model." (PMID 36450665, 2023). "The protective roles of G3BP1 and mTOR were testified in the in vivo disc degeneration model, which may provide potential targets for IDD treatment." (PMID 36450665, 2023).
Ewing sarcoma (1 paper, 2022). A small round cell tumor that lacks morphologic, immunohistochemical, and electron microscopic evidence of neuroectodermal differentiation. "YB1, a kind of RNA-binding protein, was reported to colocalize to SGs, and somewhile to regulate the components of SGs such as G3BP1 in mesenchymal tissue-derived tumors such as Ewing sarcoma and osteosarcoma." (PMID 35260638, 2022).
experimental autoimmune encephalomyelitis (1 paper, 2026). An autoimmune demyelinating disease of the central nervous system that is produced experimentally in animals by the injection of homogenized brain or spinal cord in Freund's adjuvant. "In experimental autoimmune encephalomyelitis (EAE) mice, a model of MS, TIA1 and G3BP1+ (a cell marker of SGs) SGs were upregulated in retinal neurons and optic nerve astrocytes." (PMID 41758721, 2026).
fragile X syndrome (1 paper, 2025). A genetic syndrome caused by mutations in the FMR1 gene which is responsible for the expression of the fragile X mental retardation 1 protein. "In fragile X syndrome (FXS) and autism spectrum disorder (ASD), both USP10 and G3BP1 regulate neuronal translation through FMRP interaction, and their mutations disrupt synaptic protein synthesis, impairing cognitive function and neurodevelopment." (PMID 40785597, 2025).